LRP6 (LDL receptor related protein 6)
Diseases named in the same sentence as LRP6 in open-access papers (continued):
Sharing a sentence is not in itself a finding about the gene and the disease.
prostate carcinoma (continued). "Although it is unclear whether LRP6 is up-regulated in prostate cancer, we have recently demonstrated that the LRP6 antagonist Mesd markedly inhibited Wnt/β-catenin signaling in prostate cancer PC-3 cells, and suppressed PC-3 cell proliferation in vitro and tumor growth in vivo." (PMID 22195040, 2011). "In this manner, LRP6 and CAV1 stimulate aerobic glycolysis by increasing the expression of glycolytic enzymes in prostate cancer cells." (PMID 35740528, 2022). "Alternatively, in prostate cancer cells, CAV1 interacts with LRP6 to stimulate the IGF-IR/IR/Akt/mTORC1 pathway and promote glycolysis by increasing the expression of glucose transporters and glycolytic enzymes." (PMID 35740528, 2022). "CAV1 also interacts with the low-density lipoprotein receptor protein 6 (LRP6) and stimulates the kinase activities of the insulin and IGF-I receptors (IGF-IR/IR) in PC-3 cells, as well as in primary human prostate cancer tumors and metastases." (PMID 35740528, 2022). "Niclosamide and silibinin inhibit LRP6 expression and phosphorylation, block Wnt3a-induced β-catenin accumulation, and inhibit Wnt/β-catenin signaling in HEK293 cells, prostate cancer PC-3 and DU145 cells, and breast cancer MDA-MB-231 and T-47D cells." (PMID 26369691, 2015). "In prostate cancer, immunoprecipitation and signaling studies showed that CAV1 interacts with insulin- and IGF-1 receptors (IR/IGF-1R), and can stimulate IR kinase activities by also interacting with low-density lipoprotein receptor-related protein 6 (LRP6)." (PMID 27852311, 2016). "The Mesd C-terminal region peptide and the full-length Mesd protein block Wnt3a-induced Wnt/β-catenin signaling in LRP5- and LRP6-expressing cells, inhibit Wnt/β-catenin signaling in human breast HS578T cells and prostate cancer PC-3 cells, and inhibit cancer cell proliferation." (PMID 26369691, 2015). "Prostate cancer cells (PC-3) stimulated by Wnt ligands (Wnt5A, Wnt10B) were analyzed by Cy3-PLA for the co-localization of FZD6 and co-receptors (canonical: LRP6, non-canonical: ROR1) at the single-cell level." (PMID 34769487, 2021).
Alzheimer disease (16 papers, 2012 to 2024). A progressive, neurodegenerative disease characterized by loss of function and death of nerve cells in several areas of the brain leading to loss of cognitive function such as memory and language. "Given that a reduction in the Wnt canonical coreceptor, LRP6 has been associated with aging and the late onset of AD 13, the LRP6 protein level was quantified at different ages and during Alzheimer disease-like progression." (PMID 39167347, 2024). "Lrp6-val induces synapse loss in aging and in Alzheimer’s disease by inhibiting the formation of the Wnt receptor complex." (PMID 36638182, 2023). "LRP6 mutations have been detected in Alzheimer’s disease, osteoporosis syndrome, and diabetes." (PMID 35052459, 2022). "Through genome-wide screening, it was identified that a single nucleotide polymorphism (SNP) in the 1062 residue of LRP6, which converts isoleucine to valine (hereafter referred to as Ile1062Val), leads to reduced Wnt/β-catenin signaling and is implicated in Alzheimer’s disease." (PMID 34589484, 2021). "Though rs2302685 has been considered as a common functional LRP6 polymorphism, and is significantly associated with several human diseases such as Alzheimer’s disease, the effects of this polymorphism on MI risk is still unknown." (PMID 24906453, 2014). "In the DisGeNET database, LRP6, F11, CXCL10, TCF4 and IGF2 are identified as the top five genes associated with Alzheimer's disease, with association scores of 0.989, 0.981, 0.953, 0.938 and 0.914, respectively." (PMID 38350848, 2024). "Consistently, in Alzheimer’s disease patients, DKK1 is highly expressed and causes suppression of LRP6-amyloid precursor protein (APP)-mediated Wnt/β-catenin signaling, which results in accumulation of amyloid-β and synapse loss." (PMID 34589484, 2021). "Other studies on LRP6 genetic variances have so far been done in the context of variability in bone mass density, bone disorders, late-onset Alzheimer's disease, macular degeneration and cardiovascular diseases." (PMID 22393312, 2012). "In Alzheimer’s disease (AD), a neurodegenerative disorder characterized by deficient cognitive processes and the accumulation of amyloid precursor protein (APP) and amyloid-β, LRP6 mutations are considered to be pathogenic factors." (PMID 37139333, 2023). "When LRP6 is specifically deleted in the forebrain, synapse formation is suppressed while amyloid-β accumulation and neuronal apoptosis are promoted, altogether resulting in aggravation of Alzheimer’s disease symptoms." (PMID 34589484, 2021). "Connecting to Alzheimer’s disease, dementia, and amyloidosis hubs include prominent AD-associated proteins such as the low-density lipoprotein receptor-related proteins LRP1, LRP1B, LRP4, and LRP6." (PMID 33946285, 2021). "The Low-density lipoprotein receptor-related protein 6 (LRP6) gene was recently revealed to be linked with autosomal dominant inherited tooth agenesis, and a mutation at rs2302685 was previously associated with Alzheimer’s disease, LDL-cholesterol, and bone mass." (PMID 38853224, 2024). "It is well known that LRP6 (low-density lipoprotein-related receptors 6) is a co-receptor of WNT that transmits the canonical Wnt/β-catenin signaling cascade, which has been associated with many diseases including Alzheimer’s disease and coronary artery disease (CAD)." (PMID 30813608, 2019). "In particular, low exosomal levels of survival factors (i.e., LRP6, REST, and HSF1) were found in Alzheimer's disease." (PMID 28912682, 2017). "Moreover, low exosomal levels of LRP6, REST, HSF1 were found in Alzheimer's disease." (PMID 28912682, 2017).
lung cancer (14 papers, 2016 to 2024). A malignant neoplasm involving the lung. "The Lrp6–Gsk3b–β-catenin–Tcf–Ctgf autocrine axis was implicated in a study of lung cancer progression in an in vivo preclinical model." (PMID 35302849, 2022). "LRP6 polymorphisms were validated to play a role in the predisposition of the nonsmall cell lung cancer (NSCLS) in previous study." (PMID 31031810, 2019). "Our investigation revealed that Apatinib reduces the expressions of TCF, GBP, and LRP6 in the Wnt signaling pathway significantly to inhibit the pathway, thus suppressing tumor and inhibiting the progression of lung cancer." (PMID 32849930, 2020). "To examine the reliability of our axial lsFCS-based analysis for the determination of KD values of ligand-receptor interactions, we studied DKK1-eGFP binding to NCI-H1703 lung cancer cells expressing LRP6-mCherry in widely differing amounts." (PMID 32441251, 2020). "We first studied the A549 lung cancer cell line that expresses the effector LRP6 (7, 341 copy/cell) and the guide ALCAM (874, 813 copy/cell)." (PMID 29335534, 2018). "Moreover, the expression of low-density lipoprotein receptor-related proteins 5 and 6 (LRP5 and LRP6) are also upregulated in several lung cancer cells compared with the normal lung fibroblast cell, WI-38." (PMID 36293388, 2022). "Moreover, the analysis of interactions network of LRP6 with the 19 protein and its impact on lung cancer progression in Human Protein Atlas demonstrated that the “19 protein set” associate to a better prognosis in LUAD rather than that of LUSC." (PMID 34769557, 2021). "We have evaluated the method by measuring the binding of the Wnt signaling inhibitors human Dickkopf1 (DKK1) and Dickkopf2 (DKK2) to the Wnt co-receptor lipoprotein-receptor related protein 6 (LRP6) in human lung cancer (NCI-H1703) and human embryonic kidney (HEK293T) cells." (PMID 32441251, 2020). "Interestingly, we found that Trk-fused gene (TFG), previously known to regulate the cell secretory pathway and to be rearranged in thyroid and lung cancers, was strongly enriched in the proximity of Lrp6." (PMID 33299006, 2020). "In lung cancer, garcinol induces apoptosis by impairing phosphorylation of low-density lipoprotein receptor-related protein 6 (LRP6) and down regulating expression of Axin2, β-catenin, cyclin D1, and disheveled segment polarity protein 2 (Dvl2) in H441 and A549 NSCLC cell lines." (PMID 32365899, 2020). "In the present study, we observed that ART, DHA, and ARTS inhibited the expression level of Wnt5-a/b, down-regulated those of LRP6 and Dvl2, and subsequently reduced those of downstream genes mediated by β-catenin (i.e., nanog, sox2, oct3/4, and cyclin D1) in two lung cancer cell lines." (PMID 27119499, 2016). "CD248 inhibits the interaction between LRP6 and Wnt repressors IGFBP4 and LGALS3BP, increasing Wnt/β-catenin signaling in pericytes to promote angiogenesis and tumor growth in lung cancer." (PMID 38872189, 2024). "For LRP5/6, the phosphorylation of LRP6 was decreased by RASSF10, and downregulation of RASSF10 promotes lung cancer proliferation and invasion." (PMID 38872189, 2024). "Taken together the results support that MET signaling is necessary and sufficient for LRP6 regulation via ZNRF3 and in multiple lung cancer cell lines." (PMID 34590584, 2021). "In our experiments, knockdown of Kremen2 resulted in increased levels of p-LRP6 and LPR6 protein in H1703 cells while the levels of p-LRP6 and LPR6 did not change obviously in A549 cells, implying Kremen2 might play different roles in different lung cancer cells." (PMID 37270563, 2023).
triple-negative breast carcinoma (14 papers, 2011 to 2025). An invasive breast carcinoma which is negative for expression of estrogen receptor (ER), progesterone receptor (PR), and human epidermal growth factor receptor 2 (HER2). "When LRP6 is knocked-down in triple negative breast cancer cells, tumor growth is suppressed in vivo." (PMID 31382613, 2019). "In triple negative breast cancer, LRP6 was able promote tumor migration and invasion by altering the expression and function of S100A4." (PMID 30411539, 2018). "LRP-6 is highly expressed in triple-negative breast cancers and its inhibition leads to attenuated Wnt activation, proliferation, and in vivo tumor growth." (PMID 24392029, 2013). "In addition, recent study has demonstrated the upregulation of LRP6 expression in both human triple negative breast cancer (TNBC) cell lines and patients." (PMID 31031810, 2019). "LRP6 is up-regulated in human triple negative breast cancer." (PMID 23469146, 2013). "Notably, expression of the Wnt coreceptor LRP-6 is frequently upregulated in the particularly aggressive tumor entity of triple negative breast cancer." (PMID 24392029, 2013). "In triple-negative breast cancer, the CDK14/CCNY complex phosphorylates the membrane receptor LRP6 and regulates the activity of breast cancer stem cells through the Wnt/β-catenin signaling pathway, ultimately promoting the progression and metastasis of triple-negative breast cancer." (PMID 37599359, 2023).
colon cancer (13 papers, 2015 to 2025). "LRP6 was reported to be upregulated in human cancers, including lung tumor, colon tumor, HCC and to promote the progression of tumors through regulation of the Wnt/β-catenin signaling pathway)." (PMID 25797263, 2015). "Wnt activates β-catenin and induces the formation of a complex with SP1 that binds the promoter of the Axin2 gene to activate the transcription in colon cancer, and Axin2 expression is quickly suppressed following dephosphorylation of LRP6 in the lipid raft by a porcupine inhibitor." (PMID 33430034, 2021). "For example, the LRP6 knockdown may have off-target effects specifically in APC-deficient HEK293 T cells and a number of APC-mutant colon cancer cell lines, and LRP6 knockdown in these cell lines further increased Wnt signaling instead of decreasing shown by Saito-Diaz." (PMID 34000297, 2021). "Strikingly, most of the Wnt genes upregulated by HMGA1 in our murine model are also upregulated in human colon cancer, including the WNT effectors, ASCL2, AXIN2, CTNNB1, MYC, EPHB2, CD44, and ETS2 and the WNT receptors, LGR5, LRP5, and LRP6." (PMID 39895630, 2025). "Similar to LEF1, other WNT-related genes found in our RNA-seq to be regulated by MYC such as FOXQ1 and LRP6, were also transcriptionally repressed upon MYC knockdown in colon cancer cells." (PMID 31623618, 2019). "GO enrichment analysis showed that specific proteins, including TGFβ1, adenomatous polyposis coli (APC), CTNB1, low-density lipoprotein receptor-related protein (LRP) 5 (LRP5), LRP6, JAK1, ST14, and TP53BP1, were hypothetical CD151-interacting proteins in colon cancer." (PMID 33767593, 2021). "We confirmed that Lrp6 endocytosis was observed in SW480, a colon cancer cell line in which the absence of APC triggered, and APC reconstitution inhibited, Wnt signaling and Lrp6 endocytosis; this is in agreement with recent results showing that APC is a major regulator of endocytosis." (PMID 33299006, 2020).
metabolic syndrome (13 papers, 2011 to 2024). A cluster of metabolic risk factors for CARDIOVASCULAR DISEASES and TYPE 2 DIABETES MELLITUS. "Due to its role as one of the main Wnt signaling components, the dysregulation or mutation of LRP6 is implicated in several diseases such as cancer, neurodegeneration, metabolic syndrome and skeletal disease." (PMID 34589484, 2021). "Certain mutations on the Wnt ligand coreceptor lipoprotein receptor-related protein 6 (LRP6) are associated with the susceptibility of dyslipidemia, whereas in mice, Lrp6-deficiency–induced hyperlipidemia can be partially reversed by Wnt-3a administration." (PMID 31589598, 2019). "This rare mutation in the LRP6 gene is associated with dyslipidemia, hypertension and diabetes." (PMID 21241491, 2011). "Our research group was the first to discover the link between metabolic syndrome, severe hypertension, and the LRP6 gene." (PMID 38691164, 2024). "Another study by the same group showed that that the mice with the human LRP6R611C mutation developed modest dyslipidemia but advanced proliferative CAD, which could be reversed by enhancing canonical Wnt signals in LRP6 with Wnt3a injections." (PMID 33969358, 2021). "The relationship between LRP6 dysfunction and metabolic syndrome has been widely studied." (PMID 34589484, 2021). "This review highlights the exceptional opportunities to study the pathophysiologic contributions of LRP6 to metabolic syndrome and cardiovascular diseases, which implicate LRP6 as a latent regulator of lipid metabolism and a novel therapeutic target for nutritional intervention." (PMID 26046396, 2015). "Notably, the mutations were located in the second propeller domain of LRP6, essential for ligand binding, and were shown to segregate with metabolic syndrome traits in affected family members, but not in unaffected individuals." (PMID 38691164, 2024). "Most heterozygous individuals over the age of 45 had clinical manifestations of metabolic syndrome, suggesting that the impact of LRP6 mutation on mulftiple CAD risk factors is important, and the ubiquitous expression of LRP6 gene could explain pleiotropic manifestations in various tissues." (PMID 35743896, 2022).
diabetes (12 papers, 2009 to 2024). "The strong evidence supporting a causal role for dyslipidemia in diabetes comes from genetic studies of rare mutations in ABCA1, LIPE, LPL, and LRP6, showing that these lipid genes are also linked to hyperglycemia or diabetes." (PMID 35740449, 2022). "In the gastrocnemius muscle, several genes involved in the Wnt signaling pathway were downregulated by diabetes, including Wnt2, Mpc1, Npnt, and Lrp6, whereas Fzd4 was higher in muscle from D mice." (PMID 38025035, 2023). "Reduced plasma levels of Wnt1 and elevated levels of LRP6 antagonists have been reproducibly associated with the risk for CAD in patients with early onset CAD, diabetes, and hyperlipidemia in several large clinical studies." (PMID 26046396, 2015). "Moreover, the concentration of LRP6 is higher in the vitreous samples from patients with proliferative DR,149 indicating the deleterious role of LRP6 in diabetes." (PMID 34042263, 2021). "Interestingly, Towler and colleagues found that vascular smooth muscle LRP6 could inhibit the progression of diabetic arteriosclerosis in mice by restraining a novel non‐canonical Wnt/USF1 signalling, indicating a protective role of LRP6 in diabetes." (PMID 34042263, 2021).
Hypertension (12 papers, 2009 to 2024). The presence of chronic increased pressure in the systemic arterial system. "The TT genotype at the LRP6/rs12823243 locus was found to be a risk factor for the occurrence of hypertension in the present study." (PMID 39512695, 2024). "Another investigation conducted in in the United States revealed that people with mutations in the LRP6 gene had higher-than-normal serum-related markers, which may be associated with the development of essential hypertension." (PMID 39512695, 2024). "Given that the other mutants of LRP6 (P1104S) and CTSD (G316R) in hypertension patients were associated with DCM, it is possible that the patients with LRP6 (P1427Q) develop cardiac remodeling or dysfunction in response to stress such as pressure overload or ischemia." (PMID 33391533, 2021). "LRP6 (P1104S) and CTSD (G316R) were verified in DCM patients with hypertension from Tongji Hospital (Wuhan, China)." (PMID 33391533, 2021).
melanoma (12 papers, 2013 to 2025). A malignant, usually aggressive tumor composed of atypical, neoplastic melanocytes. "LRP6 activation increases β-catenin degradation and is associated with reduced 5-year survival in melanoma patients." (PMID 30909648, 2019). "Molecular docking studies were conducted in the different proteins (Fz4-CRD, LRP6, GSK3β) of the Wnt signaling pathway and Protein Kinase B/Akt for the isolated compound to investigate the possible pathway to inhibit melanoma." (PMID 40341615, 2025). "In summary, our research indexed that miR-610 had a function of tumor suppressor in regulating the proliferation, cell cycle and apoptosis of melanoma via targeting LRP6." (PMID 29228616, 2017). "The biological function of miR-610 on melanoma cells was abrogated by alternation of LRP6 expression." (PMID 29228616, 2017). "In general, these results uncovered that direct restraint of LRP6 make miR-610 become a tumor suppressor acting on proliferation, cycle progression and apoptosis inhibition of melanoma." (PMID 29228616, 2017). "FER may contribute to melanoma metastasis through phosphorylation and consequent inhibition of the low-density lipoprotein receptor-related protein 6 (LRP6)." (PMID 30909648, 2019). "Throughout the data, a conclusion could be obtained that LRP6 was a direct downstream target of miR-610 in melanoma." (PMID 29228616, 2017). "In addition, we performed western blot and found that LRP6 was increased in a panel of melanoma cell lines compared HPM (P<0.05)." (PMID 29228616, 2017). "The accumulation of LRP6 in melanoma cells was also negatively regulated by miR-610." (PMID 29228616, 2017). "In clinical samples of melanoma, miR-610 inversely correlated with LRP6." (PMID 29228616, 2017). "Costaining of CD31 and LRP6 in B16F10 melanoma tumors showed vasculature-specific LRP6 expression." (PMID 24091497, 2014). "Moreover, it can be found that LRP6 expresses excessively in different cancers, including melanoma." (PMID 29228616, 2017). "In A375 human malignant melanoma cells, arbutin at high concentration (1 mM) up-regulated 88 genes and down-regulated 236 genes, including genes (AKT1, CLECSF7, FGFR3, and LRP6) controlling cell cycle progression, hence, suggesting that it may act similarly on neutrophils." (PMID 32731392, 2020). "Moreover, the data showed the expression of LRP6 in melanoma tissues was significantly higher than that in non-tumor tissues (P<0.05)." (PMID 29228616, 2017).